CD28 (CD28 molecule)
Diseases named in the same sentence as CD28 in open-access papers (continued):
Sharing a sentence is not in itself a finding about the gene and the disease.
tumor (continued). "This may be important in the context of TILs expressing varying levels of CD28, CD226, PD-1, and TIGIT, and myeloid or tumor cells expressing PD-L1 and PVR." (PMID 35263569, 2022). "Moreover, we have demonstrated that incorporating CD28 signaling in CAR MUC1 upregulated the immunosuppressive cytokines, IL-4 and IL-10, upon encountering the targeted tumor cells." (PMID 36457849, 2022). "More importantly, the apoptosis rate in HuCCT1 or RBE cells pretreated with ERKi was enhanced after co-culture with CD3/CD28-activated CD8+T cells compared to that in the control group, which was manifested by an increase in tumor cell apoptosis rate detected by the CCK-8 assay or flow cytometry." (PMID 35305624, 2022). "Considering T cell exhaustion, the constructions with anti-CAIX CD28 CAR and anti-PD-L1 secretion and with 4-1BB CAR with or without anti-PD-L1 secretion showed reduced co-expression of PD-1, TIM-3, CTLA-4, and CD39 in viable tumor-infiltrating T cells." (PMID 35628256, 2022). "No significant change in tumor growth was observed when mice were treated with an anti-CD28 blocking antibody." (PMID 35379805, 2022). "In this context, it is important to again emphasize that PVR is widely expressed, even by most tumor cells, suggesting that CD226 activation may participate in the T cell effector activity more so than CD28, whose activating ligand is limited to immune cells." (PMID 35263569, 2022). "To determine if FasL expression on ID8VEGF tumor cells also induces CD8 T cell death, we co-cultured wild type ID8VEGF cells with P14 CD8 T cells previously activated in vitro with anti-CD3 and CD28 antibodies (±pretreatment with FasL-blocking antibody), and stained for CC3 in T cells 3 days later." (PMID 35264436, 2022). "On the other hand, the VM index could upregulate immune checkpoints including CD28, CD86, BLTA and CD40LG to inhibit immune response, thus leading to tumor immune escape." (PMID 36505458, 2022). "To this end, we developed a novel chimeric receptor that can recognize CD80 and CD86 as tumor antigens on malignant B cells by combining the extracellular and transmembrane domains of CTLA4 with the intracellular signaling domains of CD28 and CD3z and explored its potential in cancer treatment." (PMID 33868277, 2021). "The costimulatory molecule, CD28, induced and increased production of IL-2, enhancing the clonal expansion and endurance of CAR T cells that, when combined with 4-1BB/CD137, were more efficient in INF-γ production and lysis of tumor cells." (PMID 35011678, 2021). "CAR T cell-induced tumor cytotoxicity was generally dependent on target antigen expression level for either CAR construct used, except that CAR T cells equipped with CD28 costimulation achieved equivalent cytotoxicity against cells expressing high or intermediate antigen levels." (PMID 34771652, 2021). "Superior anti-tumor activity of pCAR H/T cells was observed in mice with an established MDA-MB-468 xenograft or a HER2-overexpressing derivative, when compared with 2G (CD28; 41BB) or 3G controls." (PMID 35028604, 2021). "Additionally, agonistic aptamers against 4-1BB, OX40, CD28, and CD40 were developed by the Gilboa laboratory with similar anti-tumor effects in mice to those of mAbs." (PMID 33868786, 2021). "Compared to cells with re-expression of vector or non-glycosylated B7H3, cells with re-expression of glycosylated B7H3 were more resistant to killing by CD3/CD28-activated human T cells, as confirmed by the decreased percentage of lysed (cleaved caspase-3+ and LDH+) tumor cells." (PMID 33976130, 2021). "CD28 and CTLA-4 share a pair of ligands, CD80 and CD86, that are expressed on APCs or tumor cells." (PMID 34439774, 2021). "Protein molecule combinations of CD28-costimulatory receptor-TAA bispecifics with CD3-bsTCEs, providing sustained T-cell proliferation, markedly improved antitumor activities in a variety of tumor models." (PMID 33808165, 2021).
tumor (continued). "Overall, combining CD28 and CD40/CD40L effects within a chimeric CD40L:CD28 design shows promise to deliver CD40 activation to the TME together with improved T cell functionality for tumor attack." (PMID 34912334, 2021). "In addition to targeting two different TAAs, one of BiTE antibodies can also target inhibitory immune checkpoints to overcome adaptive immune escape of tumor cells, mainly PD-L1, thus the SMITE pair was composed of CD3/TAA BiTE and CD28/PD-L1 BiTE." (PMID 34039409, 2021). "The tumor infiltrating T cells (both CD4+ and CD8+) of plinabulin-treated mice were functional, with increased capacity to produce intracellular IFN-γ, compared to control, upon ex vivo re-stimulation with anti-CD3 and anti-CD28 monoclonal antibodies (mAbs)." (PMID 33747968, 2021). "Studies with dual CAR-T cells containing distinct CAR molecules with anti-HER2 scFv-CD28-CD3z (HER2 scFv-CD28-CD3z) and IL13Rα2 scFv-CD28-CD3z, or CD19 scFv-41BB-CD3z and CD123 scFv-41BB-CD3z, or CD19 scFv-OX40-CD3z and CD22 scFv-41BB-CD3z showed enhanced anti-tumor efficacy." (PMID 34830003, 2021). "In summary, tumor-specific CD8+ T cells in patients with NSCLC demonstrate divergent differentiation fates toward Temra subset, largely with two distinct phenotypes based on the expression of CD27 and CD28 (CD27−CD28− DN and CD27+CD28+ DP)." (PMID 34593620, 2021). "Checkpoint blockade targeting the PD-1/PD-L1 axis exerts its immunomodulatory function by alleviating in situ suppression of existing tumour-reactive T cells, as PD-1 signaling impairs both TCR/CD3- and CD28-mediated stimulatory and co-stimulatory signal integration, respectively." (PMID 34439399, 2021). "Similarly, a TriTCE which engaged with CD3, CD28 and TAA in a single molecule was recently developed to enhance both T cell activation and tumor targeting with outstanding preclinical efficacy." (PMID 33808165, 2021). "To examine whether T cells become functionally impaired with tumor progression, we evaluated their cytokine production after in vitro restimulation with antibodies against CD3 and CD28." (PMID 33408092, 2021). "Tumor expression of immune checkpoint molecules like PD1, PD-L1 (which binds to PD-1), and CTLA4 (a T-cell immune suppressant that counteracts the stimulatory activity of CD28) are biomarkers of interest to correlate with response to ICI." (PMID 34921236, 2021). "The pMHC‐I and anti‐CD28‐functionalized MNCs@MφCM could efficiently expand and stimulate CD8+ T cells ex vivo and guided reinfused CTLs to tumor tissues through magnetic control, allowing the MRI of the particles." (PMID 33898169, 2021). "While CD28 and 4-1BB cytoplasmic domains appear both critical for CAR T-cell activity, other co-stimulatory domains are reported to regulate the metabolism and to potentiate the anti-tumor activity of the CAR T-cells." (PMID 33374128, 2020). "Naïve CD8+ T cells were stimulated with anti-(CD3+CD28) mAbs-coated dynabeads for 48 hrs with or without culture supernatant from different tumor cell lines." (PMID 32122466, 2020). "CD28 CD19-specific CAR-T cells co-transduced with PD-1 DNR showed the improved function of T cells in vitro and long-lasted T cells in vivo with higher efficacy and better control of tumor cells." (PMID 33167514, 2020). "B7 family receptors, including CD28 and CD279 (PD-1), generally correlated positively with a number of T-cell markers, likely reflecting the expression of the B7 family receptors by the tumour-infiltrating T-cells." (PMID 32245446, 2020). "Dual-targeting CAR-T cells coexpressing GPC3 and asialoglycoprotein receptor 1 (ASGR1, a liver tissue-specific protein) targeting CAR’s featuring CD3 zeta chain (CD3ζ) and 28BB (containing both CD28 and 4-1BB signaling domains) have been tested in a GPC3+ASGR1+ HCC tumor xenograft mouse model." (PMID 32968061, 2020). "The inflamed TME was characterized by higher expression of PDCD1, CTLA4, CD28, (PD-L1) CD274, PD-L2, and lower tumor mutation burden than non-inflamed TME." (PMID 32528935, 2020).
tumor (continued). "Since BiTE activates T cells via CD3 without a CD28 co-stimulation, it activates effector T cells, which exhibit tumor cell killing activity without a CD28 co-stimulation, but not naïve T-cell clones." (PMID 32132638, 2020). "In the case of anti-CD19 CAR T cells, human CD8α hinge and transmembrane molecules did not promote efficacies differently against tumor xenografts but induced lower cytokine levels compared with CD28 hinge and transmembranes." (PMID 33322408, 2020). "Using a xenograft model of human melanoma, it was shown that tumour-specific T cells expressing a hybrid molecule containing the TIGIT extracellular domain fused to the CD28 intracellular domain displayed enhanced production of IFN-γ and TNF-α and improved tumour control." (PMID 32708397, 2020). "When compared to CD28, 4-1BB co-stimulated CARs showed slower onset of cytotoxicity, but longer durability and accumulation of CAR cells over time, which ultimately resulted in comparable efficacy but slower kinetics of the anti-tumor response." (PMID 32429316, 2020). "The magnitude and the breadth of stimulatory molecules in comparison to inhibitory counterparts, as exemplified here by a balance of CD28 and CTLA-4-derived signals, is critical to T cell activation and tolerance, and represents a window of opportunity for clonal selection during tumor evolution." (PMID 32117295, 2020). "A rational approach is to use tumor-localized implants loaded with tumor-specific lymphocytes that contain additional T cell-activating biologicals (such as activating anti-CD3, anti-CD28, and anti-CD137 antibodies) and T cell stimulatory cytokines (like IL-2 or IL-15)." (PMID 32942725, 2020). "Further investigations are needed to delineate the role of (a) cellular components (regulatory cells, natural killer cells, etc.)that include costimulatory versus coinhibitory molecules, (b) molecular components (CD28, CD86, CD80, etc.), and (c) cellular mechanisms involved in anti-tumor response." (PMID 32326142, 2020). "MPE-resident CD8+ T cells were co-cultured with autologous monocyte or tumor containing non-hematopoietic cells after 24-h incubation in IL-2 or IL-2 plus anti-CD3/CD28 activating microbeads." (PMID 32867034, 2020). "This is not surprising because PD-1 blockade successfully re-invigorates anti-tumor T cell responses, yet the majority of tumors do not express B7.1 or B7.2 proteins, the ligands for CD28." (PMID 33077516, 2020). "Activation of CD28 on CD8+ TILs is needed to support TIL proliferation and anti-tumor immunity." (PMID 32690667, 2020). "We generated CD28-, 41BB-, and MC-CAR T cells and demonstrated that MC-CAR T cells have greater proliferative capacity and antitumor activity in repeat stimulation assays and in tumor models in vivo." (PMID 33148882, 2020). "Furthermore, moDCs in αPD1 treated patients show enrichment for genes related to effective anti-tumor immunity, including MHC class II antigen presentation, interferon gamma signaling and CD28 co-stimulation." (PMID 32690667, 2020). "In the case of a CD28 knock-out, we observed that 80% of the tumor cell population persists at t=280 h, sign of a failure of the ICD-inducing treatment (knowing that the tumor cell population is initially set to represent 80% of the total number of cells at the beginning of the simulation)." (PMID 33281620, 2020). "Despite we detected PD-L1 expression on activated T cell or CAR-T cells, however, we failed to observed PD-L1 expression on CARPD-L1z T cells no matter being activated by CD3 and CD28 antibodies or PD-L1+ tumor cells." (PMID 32514352, 2020). "For the non-irradiated tumor in β2-AR KO mice, we noted a significant increase in expression of several genes including Cd28, Il2, and Zap70; genes showing the greatest decrease included genes which can inhibit effector function (including Il6 and Il10)." (PMID 32286326, 2020).
tumor (continued). "To test whether T-cell activation preceding the tumor cell coculture could enhance the tumor-killing ability of the OT1-iT cells, we stimulated the primary OT1-iT cells or the primary WT-T cells with CD3/CD28 antibodies for 4 days in vitro." (PMID 32669292, 2020). "Interestingly, in-vivo anti-tumor function of pmel-I and OT-1/2 T cells was improved by CTLA-4:CD28 expression, but was highly dependent on the presence of CD4+ T cells, and was linked to their elevated production of IL-2." (PMID 32570906, 2020). "In the univariate analyses, high CD8+CD28+ T-cell counts (OR 0.12, 95% CI 0.03–0.48; P = 0.003), CD4/Treg ratio (OR 0.24, 95% CI 0.06–0.90; P = 0.035), and BED10 (OR 0.91, 95% CI 0.84–0.99; P = 0.032) predicted tumor response to SABR." (PMID 30971280, 2019). "Next, to confirm that Stat4−/− T cells from HNSCC tumor bearing mice were deficient in their ability to produce IFN-γ, we re-stimulated splenocytes from tumor bearing WT and Stat4−/− mice with anti-CD3 and anti-CD28 antibodies, then determined IFN-γ production by ELISA." (PMID 32010142, 2019). "Our investigation revealed that the CD8+CD28+ T-cell count correlated positively with tumor response to SABR in patients with lung metastases, which was consistent with previous findings and the anti-tumor function of these particular immune cells." (PMID 30971280, 2019). "Specifically, SABR could facilitate the immunogenic cell death of cancer cells, release tumor antigens, recruit antigen-presenting cells to present antigens to T cells, and activate the antitumor effect of CD8+ T cells through TCR and CD28 signals." (PMID 30971280, 2019). "Tumor samples from HPK1 KD mice demonstrated significantly upregulated key immune cell markers involved in mediating anti-tumor immunity, including CD4, CD8, IFNγ, TNFα, Granzyme B, CD28, CD11c and CD11b." (PMID 30913212, 2019). "Successful in vivo studies using 4-1BB/CD28 third generation CARs include an ICAM-1 CAR for a mouse model of thyroid cancer, a GPC3 CAR in a patient derived xenograft of model of HCC, and a VEGFR2 CAR against multiple tumor types in vivo." (PMID 30804938, 2019). "Values of few populations (CD45RO+ in Frozen PBMC, and CD45+, CD3+TIGIT+, CD3+CTLA4+, and CD3+CD28+ in tumor biopsies) did not give rise to statistically equivalent results using equivalence test." (PMID 31165047, 2019). "No significant changes in the expression of CD28 or NKG2D was observed on CD4 T cells in tumor draining LN." (PMID 31446896, 2019). "Control cultures containing tumor fragments but without IL-2 or CD3/CD28 Dynabeads showed no expansion of TILs." (PMID 31398192, 2019). "In univariate logistic analyses, high CD8+CD28+ T-cell counts (OR 0.12, 95% CI 0.03–0.48; P = 0.003), CD4/Treg ratio (OR 0.24, 95% CI 0.06–0.90; P = 0.035), and BED10 (OR 0.91, 95% CI 0.84–0.99; P = 0.032) predicted a 1-month tumor response to SABR." (PMID 30971280, 2019). "In contrast, the neoantigen-specific T cells found within the non-responder group more often displayed a memory-like phenotype (CD27-high, CD28-high, and CD127-high) and may be less effective in carrying out an anti-tumor response." (PMID 31511069, 2019). "For example, a PD-1/CD28 switch receptor was engineered into mesothelin-BBζ or PSCA-BBζ CAR T cells, and both switch-receptor CARs performed significantly better than wild type CARs at eradicating tumor in xenograft NSG mouse models." (PMID 30804938, 2019). "Therefore, we incorporated CD28 costimulation and IL-15 culture into our in vitro differentiation model to generate memory phenotype OT-1 T cells for ACT to EL4-OVA tumor-bearing mice." (PMID 31335326, 2019). "We have adopted this strategy and devised chimeric receptors where CD28-signaling domains were fused to the extracellular binding domains of either CD2, CD226 or TIGIT and thus can be engaged by CD58 or CD155 expressed on the tumor targets." (PMID 29707134, 2018).
tumor (continued). "We reproduced this finding with archived tumor samples from additional experiments which had investigated T cell therapy using two other GD2-specific 2nd generation CARs with alternative costimulatory domains, either CD28 or 2B4." (PMID 29464090, 2018). "To explore whether stimulation strength would also affect the tumor killing efficiency, we adoptively transferred OT1 T cells stimulated with just anti-CD3 and anti-CD28 antibodies." (PMID 29360859, 2018). "We report an assessment of CD28 profiling in various tumor indications that show that CD28 expression is most significantly lost on central memory and effector memory CD8+ T cells in the tumor." (PMID 30400835, 2018). "Despite the loss of this critical co-stimulatory receptor, a cytotoxic profile (CD107a) is retained on CD28-negative CD8+ T cells across many tumor indications." (PMID 30400835, 2018). "In different tumor mouse models, T cells expanded from OKT3-28BB/CD86/4-1BBL RNA electroporation showed anti-tumor activities superior to those of OKT3/IL-2 T cells and similar to those of CD3/CD28 Dynabead T cells." (PMID 28523432, 2017). "Comparative analysis showed that the PD-1 level was significantly higher than that of CD28 in the tumor tissues but not in nontumor tissues." (PMID 28061450, 2017). "The splenic CD11b+ MDSCs from tumor-bearing mice were isolated, treated with inhibitors of glycolysis ex vivo and then added to splenocytes from Balb/c mice stimulated with anti-CD3/CD28 antibodies." (PMID 28492541, 2017). "Irradiation increased the ability of tumor cells to suppress nonspecific stimuli (anti-CD3/CD28 antibody)-mediated T cell proliferation, and anti-PD-L1 attenuated the ability of T cell suppression induced by irradiated tumor cells." (PMID 26804478, 2016). "Despite a high expression of the transcription factor T-bet, CD8+ T cells from the tumor site failed to produce IFNγ after CD3/CD28 in vitro restimulation and displayed a reduced ability to degranulate in response to T cell stimuli." (PMID 27809856, 2016). "Irradiation increased the ability of tumor cells to suppress nonspecific stimuli (anti-CD3/CD28 antibody )-mediated T cell proliferation, and anti-PD-L1 attenuated the ability of irradiated tumor cells-mediated T cell suppression." (PMID 26761210, 2016). "Similar approaches have been developed for PD-1, which is another inhibitory receptor that suppresses T cell responses independent of CD28 but dependent of its ligands PD-L1 and PD-L2, which are abundantly expressed by several types of tumor cells." (PMID 27092248, 2016). "More interestingly, in comparison with CD3/CD28 bead-stimulated T cells, T cells that were expanded by a rapid T-cell expansion protocol (REP) showed enhanced anti-tumor activities for both CAR and BiTE RNA-electroporated T cells both in vitro and in a Nalm6 mouse model (P<0.01)." (PMID 27258611, 2016). "For a mitogen-driven assay, CFSE-labeled splenocytes from heathy C57BL/6 mice were incubated with anti-CD3 and anti-CD28 antibodies and cultured with rPAUF-treated or untreated MDSCs from EL4 tumor-bearing mice at different effector: target ratios (0:1, 0.1:1, 0.5:1, and 1:1)." (PMID 27322081, 2016). "In preclinical experiments, the tumor specificity of MILs, following anti-CD3/CD28 activation, was observed in all patients examined, and one patient in whom a tetramer existed for the HLA-A2+ PR-1 peptide, the precursor frequency of MILs went from 1 to 17.8% following expansion (unpublished data)." (PMID 27066005, 2016). "CD28 costimulation has been shown to induce optimal proliferation of murine NK cells and enhance IFN-γ secretion, and the CD28 pathway has been shown to be involved in cytotoxic killing of tumor cells." (PMID 25964782, 2015). "Tumor-reactive T cells from lymph nodes can be further expanded ex vivo in the presence of an anti-CD3 stimulus with or without CD28 engagement in addition to interleukin-2 to treat established tumors." (PMID 25990075, 2015).